CALHM4 (calcium homeostasis modulator family member 4)
Description:
May assemble to form gap junction channel-like structures involved in intercellular communication. Channel gating and ion conductance are likely regulated by membrane lipids rather than by membrane depolarization or extracellular calcium levels.
Synonyms: C6orf78; FAM26D; FLJ32239
Tractability: Small molecule: a structure with a bound ligand is known. Antibody: UniProt places it where antibodies can reach, with high confidence; UniProt predicts a signal peptide or a membrane-spanning region; its Gene Ontology location is reachable by antibodies, with medium confidence; the Human Protein Atlas places it where antibodies can reach.
Gene: Protein-coding gene on chromosome 6 (116,529,013 to 116,561,127, forward strand). Ensembl gene ENSG00000164451.
Subcellular location: Cell membrane
Subcellular location (Human Protein Atlas): Plasma membrane
Gene Ontology:
Molecular function: monoatomic cation channel activity
Biological process: ATP export; monoatomic cation transmembrane transport
Cellular component: plasma membrane
Genetic constraint (gnomAD): Loss-of-function variants: 23 observed, 20.97 expected, observed/expected ratio (o/e) 1.1, 90% interval 0.79 to 1.55. The upper end of that interval is the gene's LOEUF score, 1.55, which puts it in group 6 of 6, group 1 being the genes least tolerant of losing a copy. Missense variants: 344 observed, 392.31 expected, observed/expected ratio (o/e) 0.88, 90% interval 0.8 to 0.96. Synonymous variants: 127 observed, 143.99 expected, observed/expected ratio (o/e) 0.88, 90% interval 0.76 to 1.02.
Homologues: Orthologues: chimpanzee CALHM4 (99% identical), macaque CALHM4 (95% identical), dog CALHM4 (87% identical), pig CALHM4 (83% identical), rabbit CALHM4 (81% identical), rat Calhm4 (78% identical), mouse Calhm4 (77% identical), guinea pig CALHM4 (73% identical), tropical clawed frog calhm4 (45% identical), Caenorhabditis elegans clhm-1 (23% identical). Paralogues in human: CALHM2 (29% identical), CALHM6 (27% identical), CALHM5 (26% identical), CALHM1 (24% identical), CALHM3 (22% identical).
Diseases named in the same sentence as CALHM4 in open-access papers:
CALHM4 is named in the same sentence as 1 disease in open-access papers, as found by Europe PMC text mining. Sharing a sentence is not in itself a finding about the gene and the disease.
CALHM4 shares sentences with these, for which no sentence is quoted: preeclampsia (2 papers).